TNFRSF1B (TNF receptor superfamily member 1B)
Diseases named in the same sentence as TNFRSF1B in open-access papers (continued):
Sharing a sentence is not in itself a finding about the gene and the disease.
TNFRSF1B also shares sentences with these, for which no sentence is quoted: Autoimmunity (30 papers); Arthritis (28); multiple sclerosis (26); colon carcinoma (24); experimental autoimmune encephalomyelitis (21); type 1 diabetes (19); chronic kidney disease (15); diabetic kidney disease (15); inflammatory bowel disease (13); malaria (12); acute myeloid leukemia (11); neurological diseases (11); viral infection (11); ischemic stroke (10); atherosclerosis (9); cutaneous T-cell lymphoma (9); cervical carcinoma (8); demyelination (8); acute kidney injury (7); graft versus host disease (7); ischemia (7); liver disease (7); multiple myeloma (7); Allergy (6); bacterial infection (6); clear cell renal carcinoma (6); cognitive deficits (6); depression (6); hepatocellular carcinoma (6); influenza (6).
A further 239 diseases each share a sentence with TNFRSF1B in 6 papers or fewer.